SOD2 (superoxide dismutase 2)
Diseases named in the same sentence as SOD2 in open-access papers (continued):
Sharing a sentence is not in itself a finding about the gene and the disease.
glaucoma (7 papers, 2009 to 2024). Increased pressure in the eyeball due to obstruction of the outflow of aqueous humor. "Interestingly, target annotation analysis revealed validated interactions of hsa-miR-6515-3p with eight genes and two out of them, PRDX6 and SOD2, were previously associated with response to oxidative stress, which is a major cause of glaucoma pathogenesis." (PMID 33929592, 2021). "virus-mediated pretreatment with SOD2 attenuated oxidative stress and reduced mitochondrial dysfunction in RGCs and the ON in glaucoma." (PMID 30524222, 2018). "Oxidative stress is proposed to be involved in the etiology of glaucoma and increased expression of the SOD2 gene was observed in the aqueous humor of glaucoma patients." (PMID 19754948, 2009). "Targeting of PRDX6 and SOD2 by hsa-miR-6515-3p could be a possible mechanism promoting cellular senescence and impairing antioxidant ability, thus also contributing to glaucoma." (PMID 33929592, 2021). "Additionally, many polymorphisms identified in SOD2 and PRDX6 genes may potentially influenced interactions with miRNAs affecting susceptibility to glaucoma." (PMID 33929592, 2021). "Moreover, gene therapy with SOD2 and catalase decreases RGC death in a mouse model of glaucoma (optic nerve crush)." (PMID 30373222, 2018). "The objective of this study was to investigate association of several genes that have not been subject to an association study with glaucoma cases so far but might be functionally linked to glaucoma pathogenesis (RDX, SNX16, MFN1, MFN2, PARL, SOD2)." (PMID 19754948, 2009).
liver diseases (7 papers, 2016 to 2025). "Many reports have suggested that SOD2 is important for scavenging the superoxide produced in mitochondria, with impaired SOD2 function causing mitochondrial dysfunction, which leads to aging-related neurodegenerative diseases and liver disorders." (PMID 37416477, 2023). "SOD2-rs4880G was significantly associated with susceptibility of HBV-induced liver disease under univariable analysis in the dominant genetic model, but after adjusting for confounders, the loci’s protective effect was not significant (P = 0.080)." (PMID 31969899, 2019). "We then determined the genotypes in each group for CYBA-rs4673, NCF4-rs1883112, NOX4-rs1836882, rs3017887, SOD2-rs4880, and GCLM-rs41303970, and evaluated the association between these variants and HBV-induced liver diseases." (PMID 31969899, 2019). "Nuclear factor erythroid 2-related factor 2 (Nrf2) regulates antioxidant machinery and expresses a variety of antioxidant genes, including heme oxygenase-1 (HO-1) and superoxide dismutase 2 (SOD2), which alleviate oxidative stress and inflammatory responses in liver diseases." (PMID 32992548, 2020). "Nrf2 signaling may compensatorily increase the response to acute stress, modulating expression of several oxidative damage genes, including HO-1 and SOD2 that are protective in diverse models of liver diseases." (PMID 32194395, 2020). "We can only conclude that Nox4-rs1836882, rs3017887, NCF4-rs1883112, SOD2-rs4880, and GCLM-rs41303970 have statistically significant interactive functions in the development of HBV-induced liver disease." (PMID 31969899, 2019).
medulloblastoma (7 papers, 2015 to 2023). A malignant, invasive embryonal neoplasm arising from the cerebellum. "In this assessment, pediatric medulloblastoma patients who received cisplatin chemotherapy and had the C-allele of SOD2 rs4880, which has been associated with noise-induced hearing loss 16, had an increased susceptibility to ototoxicity." (PMID 26400460, 2015). "Therefore, we aimed to determine the association between SOD2 variants and ototoxicity among cisplatin-treated childhood medulloblastoma patients." (PMID 26400460, 2015). "Therefore, we examined SOD2 variants in association with ototoxicity among cisplatin-treated childhood medulloblastoma patients." (PMID 26400460, 2015). "While some authors using recombinant SOD2 protein showed tyrosine nitration and tyrosine oxidation upon treatment with peroxynitrite, protein biochemical analyses of SOD2 protein species from medulloblastoma cells showed tryptophan oxidation and histidine oxidations but no tyrosine nitration." (PMID 27630759, 2016).
myocardial ischemia (7 papers, 2019 to 2025). A disorder of cardiac function caused by insufficient blood flow to the muscle tissue of the heart. "The validation results using the Western blot demonstrated that in the myocardial ischemia group, the SOD2 level was significantly reduced compared to the Sham group." (PMID 39458930, 2024). "The activation of PPARα protects myocardial cells by increased expression and activation of superoxide dismutase (SOD1, SOD2) and catalase and suppresses the generation of ROS in myocardial ischemia." (PMID 30911353, 2019).
tongue squamous cell carcinoma (7 papers, 2010 to 2025). A squamous cell carcinoma that arises from the tongue. "In the stem-like cells population of tongue squamous cell carcinoma, SOD2 was suggested to mediate its migration and invasion." (PMID 31629402, 2019). "miR-222 has been identified as a potential negative regulator of SOD2 expression through direct binding to the 3′ UTR in tongue squamous cell carcinoma." (PMID 29099803, 2017). "MYC proto-oncogene (c-myc)-dependent increases in SOD2 expression lead to a more migratory and invasive phenotype, and enhance stem cell properties of tongue squamous cell carcinoma cells." (PMID 29099803, 2017). "An example is the regulation of SOD2 by c-myc in tongue squamous cell carcinoma." (PMID 29099803, 2017). "Some reports show that SOD2 can induce the migration and invasion of tongue squamous cell carcinomas, while others have shown that SOD2 is lower in cancer cells and that the reduced SOD2 expression might be related to malignant cancer progression." (PMID 25402510, 2015). "A plausible explanation for the earlier conflicting statement is that increased OS, resulting from the excessive production of H2O2, contributes to the aggressiveness of tongue squamous cell carcinoma (while concurrently elevated SOD2 expression may not be causative)." (PMID 38525070, 2024).
cognitive decline (6 papers, 2016 to 2025). "Thus, a remaining important question is if possession of one or more SOD2 rs4880-T alleles is also associated with greater risk for cognitive decline with therapy." (PMID 27099827, 2016). "The overexpression of SOD2 in AD mouse models reportedly reduces Aβ deposition and prevents memory deficits, whereas mutant AD mice with depleted SOD2 expression show increased Aβ levels and accelerated synaptic dysfunction and cognitive decline." (PMID 36275011, 2022).
diabetic neuropathy (6 papers, 2008 to 2025). A chronic, pathological complication associated with diabetes mellitus, where nerve damages are incurred due to diabetic microvascular injury involving small blood vessels that supply these nerves, resulting in peripheral and/or autonomic nerve dysfunction. "SOD2 increases osteoblast differentiation and bone formation and protects neurons in diabetic neuropathy." (PMID 35328013, 2022). "For example, SOD2 overexpression in primary dorsal root ganglion cultures or in mice protected cellular injury and prevented development of signs of diabetic neuropathy (DN) respectively." (PMID 20976160, 2010). "Genes encoding the enzymes (superoxide dismutase 2, mitochondrial) Mn-SOD and extracellular superoxide dismutase (EC-SOD) were found to be associated with the pathogenesis of diabetic polyneuropathy (DPN)." (PMID 19471607, 2008). "Whether cutaneous SOD2 levels can predict the development of diabetic neuropathy will be determined during the prospective GDS follow-up." (PMID 27053136, 2016). "Moreover, NaHS attenuated degeneration of dorsal root ganglion neurons and sciatic nerve axons in diabetic neuropathy by activating antioxidant enzymes such as superoxide dismutase (SOD) and superoxide dismutase 2 (SOD2) and downregulating aldose reductase expression." (PMID 41465271, 2025).
fatty liver (6 papers, 2020 to 2025). "A single dose of human atMSC that had been genetically modified with adenovirus constructs to overexpress one of two antioxidants, either superoxide dismutase 2 (Sod2) or catalase (Cat), improved hepatic steatosis and systemic inflammation significantly after just 4 weeks." (PMID 35860241, 2022). "Interestingly, a recent study reported that i.p. modified human adipose tissue-derived MSCs with antioxidant genes Sod2 (mitochondrial) and catalase (cytosolic) upregulated using adenoviral constructs significantly reduced liver steatosis and TG content." (PMID 32045450, 2020).
Friedreich ataxia (6 papers, 2011 to 2025). An inherited condition that affects the nervous system and causes movement problems. "Strikingly, in most cases Friedreich ataxia cells show a significant decrease in SOD2 mRNA as well, which we also found in the MEOAL patient’s cells characterized in the present work." (PMID 41372147, 2025). "It is worth noting that a decrease of SOD2 levels has been found in various cellular and animal models of Friedreich ataxia, which shares several biochemical features with MEOAL including iron overload and increased sensitivity to oxidative stress likely due to defects in FeS clusters biosynthesis." (PMID 41372147, 2025).
liver cancer (6 papers, 2014 to 2023). An epithelial or non-epithelial malignant neoplasm that arises from the liver. "It confers radioresistance to liver cancer cell lines by inducing mitophagy via superoxide dismutase 2 (SOD2) and γ-aminobutyric acid A receptor-associated protein (GABARAP)." (PMID 36826016, 2023). "Compared with matching liver and blood samples, there is also a pronounced loss of SOD2 copy number in the liver cancer tissues." (PMID 27221200, 2016). "We found that NEAT1 knockdown and NEAT1v1 overexpression resulted in the downregulation and upregulation, respectively, of SOD2 in liver cancer cells." (PMID 36826016, 2023). "SOD2 knockdown in liver cancer cell lines overexpressing NEAT1v1 activated MEK and ERK as well as P38MAPK and JNK and sensitized cells to sorafenib and lenvatinib." (PMID 36826016, 2023). "Although further in vivo and clinical studies are needed, these results suggested that NEAT1v1 switches the growth modality of liver cancer cell lines from MEK/ERK-dependent to AKT-dependent mode via SOD2 and regulates sensitivity to the molecular-targeted drugs independent of ER stress." (PMID 36826016, 2023). "Therefore, hydrogen peroxide produced by SOD2 could be involved in the activation of AKT in liver cancer cells overexpressing NEAT1v1." (PMID 36826016, 2023). "In this study, we found that circSOD2, derived from SOD2 was highly expressed in HCC patient tumor tissues and liver cancer cells compared to normal liver tissues and normal liver cells, respectively." (PMID 33234142, 2020). "In liver cancer cell lines, NEAT1 or SOD2 knockdown activates the PERK/EIF2α pathway." (PMID 36826016, 2023). "Despite the importance of SOD2 in mitochondria, to date, SOD2 has not been studied in liver cancer." (PMID 27221200, 2016).
liver fibrosis (6 papers, 2019 to 2023). "Simultaneously, the antioxidant prowess of hepatocytes in these mice experienced compromise due to a marked reduction in SOD1 and SOD2 expression, aligning with outcomes observed in CCl4-induced liver fibrosis in rats." (PMID 38132319, 2023). "Compared to the BDL group, EP administration increased the SOD2 level in liver fibrosis rats at 2 and 4 weeks (P < 0.05)." (PMID 31933629, 2019). "In brief, carriage of the ‘T’ allele in the SOD2 gene leads to less transport of MnSOD to the mitochondria, which is frequently found in non-alcoholic steatohepatitis (NASH) patients and is associated with the severity of liver fibrosis." (PMID 36555531, 2022). "Paeoniflorin could reduce cholestatic inflammation and liver fibrosis in the PBC mouse model by eliminating mtROS through the SIRT1/forkhead box O1 (FOXO1)/superoxide dismutase 2 (SOD2) signaling pathway, and thereby alleviate mitochondrial damage and inhibit NLRP3 inflammasome activation." (PMID 36969233, 2023).
osteosarcoma (6 papers, 2023 to 2025). A usually aggressive malignant bone-forming mesenchymal neoplasm, predominantly affecting adolescents and young adults. "Furthermore, suppression of GPX4 and SOD2 reversed resistance to EGFR-TKIs in NSCLC and the induction of ferroptosis by impairing STAT3/Nrf2/GPx4 signaling enhances the sensitivity of osteosarcoma cells to cisplatin." (PMID 39681067, 2024).
skin cancer (6 papers, 2009 to 2025). "A study shows that Mn-SOD deficiency (Sod2+/− deletion) increases oxidative stress, AP-1 activation, and cell proliferation after DMBA/TPA treatment, whereas Mn-SOD overexpression inhibits the development of skin tumors by decreasing AP-1 activity." (PMID 40867576, 2025).
spongiform encephalopathy (6 papers, 2006 to 2023). "We conclude that changes relating to SOD2 during prion disease are most likely secondary to the disease processes causing toxicity and do not influence the development of spongiform pathology." (PMID 34735539, 2021). "Potentially, if PrP influences SOD2 function and this function is critical for maintaining homeostasis during prion disease, its loss toward terminal disease could be responsible for the accumulating cellular damage including development of spongiform change." (PMID 34735539, 2021). "SOD2-ablated mice treated with the external synthetic SOD2–catalase mimetics extended the lifespan by three folds and rescued the mice from spongiform encephalopathies." (PMID 30337853, 2018). "However, in human prion disease studies that examined protein levels in terminal brain tissue, increases in SOD2 protein were detected, indicating that the increased SOD2 in the RML infections does mirror what occurs in human disease." (PMID 34735539, 2021). "However, if SOD2 knock-out mice are kept alive for several weeks post birth using antioxidant therapy they develop a spongiform encephalopathy reminiscent of a PrD." (PMID 34735539, 2021). "As SOD2 knock-out mice kept alive post birth using anti-oxidant therapy develop a spongiform encephalopathy, we examined the PrD pathology present in the SOD2+/- mice and WT mice infected with ME7 and 22L; representing the longest and shortest incubation periods of the strains tested respectively." (PMID 34735539, 2021). "Mitochondrial SOD/SOD2 synthetic mimetics that can cross the blood brain barrier have been shown to protect SOD2 null mice against spongiform encephalopathy that results due to the null phenotype and may have a potential use in treatment of TSEs." (PMID 23674999, 2006). "Consequently, we hypothesized that reduced levels of SOD2 may accelerate prion disease progression and play a critical role in the formation of spongiform change." (PMID 34735539, 2021). "Interestingly, SOD2 KO at astrocytes in SOD2ako mice did not lead to spongiform encephalopathy either, suggesting that either that SOD2 loss in oligodendrocytes, or SOD2 loss in more than one neurogenic lineage cell types is essential for the development of spongiform encephalopathy." (PMID 37609868, 2023). "During prion disease or prion infection of cells, changes of expression and activity of the SOD family of enzymes are seen, including a decrease in SOD2 protein levels." (PMID 29574582, 2018). "Furthermore, we propose that spongiform encephalopathy, along with inflammation, is the major cause of death in B-Sod2−/−, and the activity of neuronal SOD2 could not be compensated for by other antioxidative systems." (PMID 26301039, 2015).
age-related macular degeneration (5 papers, 2009 to 2020). Age-related loss of vision in the central portion of the retina (macula), secondary to retinal degeneration. "Knockdown of SOD2 activity in mouse RPE induced early stages of age related macular degeneration (AMD) changes and can be used as an animal model for studying AMD." (PMID 21976958, 2011). "A nonsynonymous coding variant in the manganese superoxide dismutase (SOD2) gene (V16A, rs4880) has been implicated in neovascular age-related macular degeneration (AMD)." (PMID 19753309, 2009).
cerebral infarction (5 papers, 2013 to 2024). An ischemic condition of the brain, producing a persistent focal neurological deficit in the area of distribution of the cerebral arteries. "For example, SOD2 deficiencies have previously been linked to the exacerbation of cerebral infarcts, whereas overexpression of SOD2 in transgenic mice proved to be neuroprotective." (PMID 24961414, 2013). "Increased SOD2 expression in SOD2 transgenic mice promotes the neuroprotective effect of fenofibrate on cerebral infarction." (PMID 39109777, 2024). "In this study, REL and SOD2 were highly expressed in patients with cerebral infarction at the bulk RNA, single-cell RNA, and clinical levels." (PMID 35481271, 2022).
experimental autoimmune encephalomyelitis (5 papers, 2009 to 2025). An autoimmune demyelinating disease of the central nervous system that is produced experimentally in animals by the injection of homogenized brain or spinal cord in Freund's adjuvant. "Ectopic expression studies reveal that even small changes in expression of IDO, HMOX-1, or mitochondrial superoxide dismutase (SOD2) can prevent demyelination in experimental autoimmune encephalomyelitis (EAE) animal models of MS." (PMID 19461950, 2009).
fibrosarcoma (5 papers, 2011 to 2023). A malignant mesenchymal fibroblastic neoplasm affecting the soft tissue and bone. "In the same study SOD2 upregulation was associated with enhanced metastatic potential of fibrosarcoma cells in an animal model." (PMID 25745358, 2015). "Moreover, several studies have demonstrated a peroxidative rather than antioxidative role of SODs under specific circumstances: SOD2 overexpression led to an increase of H2O2 in fibrosarcoma cells and SOD2 displays peroxidase activity in presence of high H2O2 concentrations." (PMID 35906211, 2022). "The relative mRNA expression levels of selenoprotein W (SELENOW), SEPP1, masculoaponeurotic fibrosarcoma K (MafK), CAT, SOD1, SOD2, and NAD (P)H: quinone oxidoreductase 1 (NQO1) genes in TN + SeNPs-AOS group were higher than TN group (p < 0.05)." (PMID 38001826, 2023).
lentivirus infection (5 papers, 2014 to 2025). Virus diseases caused by the Lentivirus genus. "We found that ERβ binding ability decreased to 58% as a result of HG(4d)+LG(4d) treatment compared to LG(8d) group, and this was completely restored by SOD2 lentivirus infection (↑SOD2)." (PMID 31396159, 2019). "The OVX surgery increased the ROS generation by more than 2-fold compared to Sham/CTL mice, and the E2 treatment or SOD2 lentivirus infection (↑SOD2) restored OVX-induced ROS generation." (PMID 25462070, 2014). "The results showed that the activity decreased to 51% as a result of HG(4d)+LG(4d) treatment compared to the LG(8d) group, and the lentivirus infection of either ERβ (↑ERβ), SOD2 (↑SOD2), or ERβ agonist (DPN) treatment increased SOD2 enzyme activity by 137, 124, and 142%, respectively." (PMID 31396159, 2019). "On the other hand, SOD2 protein decreased to 51% as a result of HG(4d)+LG(4d) treatment compared to the LG(8d) group, and the lentivirus infection of either ERβ (↑ERβ) or SOD2 (↑SOD2), or ERβ agonist (DPN) treatment, increased SOD2 protein level by 169, 194, and 176%, respectively." (PMID 31396159, 2019). "We investigated the effect of SOD2 lentivirus infection on the ROS generation from those aortas." (PMID 25462070, 2014). "Our data suggest that Tie2-driven SOD2 lentivirus infection is efficient and specific." (PMID 25462070, 2014). "The results showed that the SOD2 expression was only increased in endothelial cells from the heart and aorta, showing no increase in liver, kidney and hypothalamus, indicating that Tie2 driven lentivirus infection is sufficient." (PMID 25462070, 2014).